RN7SKP170 (RN7SK pseudogene 170)
Gene: Miscellaneous RNA gene on chromosome 4 (15,093,767 to 15,094,094, reverse strand). Ensembl gene ENSG00000199420.
Homologues: Orthologues: chimpanzee 7SK (93% identical). Paralogues in human: RN7SKP180 (74% identical), 7SK (73% identical), RN7SKP255 (73% identical), RN7SKP30 (73% identical), RN7SKP79 (72% identical), RN7SKP250 (72% identical), RN7SKP9 (72% identical), RN7SKP124 (71% identical), RN7SKP90 (71% identical), RN7SKP176 (71% identical), RN7SKP173 (70% identical), RN7SKP163 (70% identical), and 284 more.